TLR7 (toll like receptor 7)
Diseases named in the same sentence as TLR7 in open-access papers (continued):
Sharing a sentence is not in itself a finding about the gene and the disease.
asthma (continued). "For example, human eosinophils increase their adhesion molecule CD11b and IL-8 secretion upon exposure to R-837 and CpG DNA, suggesting TLR7/8 and TLR9 in human eosinophil could be responsible for asthma exacerbation by viral infections." (PMID 29867994, 2018). "This is consistent with the observation that, compared to non-asthmatic individuals, TLR7 function is reduced in adolescents with asthma." (PMID 28099113, 2017). "Our findings suggest that TLR7 and RLR signalling work collaboratively to optimally control the host response to pneumovirus infection thereby protecting against viral bronchiolitis and subsequent asthma." (PMID 28539639, 2017). "Bronchoalveolar lavage (BAL) cells from nonsevere asthma possess a deficient IFN response to rhinovirus infection; additionally, TLR7 dysfunction was shown in asthmatic peripheral blood mononuclear cells." (PMID 27274620, 2016). "Subjects with moderate-to-severe asthma and eosinophilic but not neutrophilic airways inflammation, despite inhaled steroids, showed reduced TLR7 and IFNλ2/3 expression in endobronchial biopsies." (PMID 26108570, 2015). "Moreover, in proof-of-concept clinical trials in humans, treatment with TLR7, TLR8 or TLR9 agonists reduces symptoms of allergic diseases such as asthma (Cytos Biotechnology AG." (PMID 23584892, 2013). "Agonists of intracellular TLRs such as TLR3 agonist poly(I:C) and TLR7/8 agonist imidazoquinoline promote activation of Th1 immune responses; the TLR9 synthetic agonists are being investigated for cancer immunotherapy, asthma and allergy therapy, and vaccine adjuvants." (PMID 23151919, 2012). "In addition, TLR7 senses single-stranded viral RNA which inhibits Th2 immune responses and eosinophilic asthma, and TLR9 detects unmethylated CpG motifs in microbial DNA molecules in the development of asthma and asthma exacerbation." (PMID 27274620, 2016). "In this study, we optimized an EAIAD mouse model that mimics allergen-driven asthma without traditional adjuvants, to test bio-mimetic nanocarriers co-delivering the OVA antigen and the TLR7/8 agonist 3M-052 on the same nanoparticle." (PMID 40951841, 2025). "Furthermore, Toll-like receptor 7 and 8 (TLR7/8) mediates the antiviral immune response by recognizing mainly viral RNA, and the increased response of the CCL13 gene to TLR7/8 agonists in the nasal mucosa of asthma patients may reflect the role of the virus in asthma progression." (PMID 37153575, 2023). "In addition to this finding, in vivo research shows that a lack of TLR7 signaling in a rhinovirus-induced asthma exacerbation leads to reduced IFN production and exaggerated Th2-driven inflammation, suggesting the role of TLR7 signaling in rhinovirus-induced asthma exacerbation." (PMID 27274620, 2016).
melanoma (67 papers, 2009 to 2026). A malignant, usually aggressive tumor composed of atypical, neoplastic melanocytes. "In this study, we aim to investigate the impact of HLJD on the efficacy of ICIs in melanoma and elucidate the underlying mechanisms based on TLR7/8 signaling." (PMID 38605368, 2024). "Anti-tumor action of TAMs is enhanced in melanoma patients when treated with TLR7 and TLR8 agonists (3M-052), which also cause the modification of M2-like TAMs into M1-like TAMs." (PMID 37138860, 2023). "TLR7 agonist treatment inhibited tumor-associated macrophages in B16F10 melanoma." (PMID 36476317, 2022). "Additionally, TLR7 activation in melanoma is associated with significant increases in: intratumoral CD8+ T and CD4+ T cells; anti-tumor macrophages, B cells, IFNγ, IFNα/β, and plasmacytoid dendritic cells, and pro-inflammatory cytokines IL6 and IL12." (PMID 32455916, 2020). "The I-IFN deficiency of pDCs might likely result from defective TLR-7/9 signaling pathways induced by soluble factors released in high amounts in melanoma patients, such as cytokines." (PMID 32731406, 2020). "Nonetheless, our observations provide important evidence that the NK phenotype can be modulated by TLR7/8 agonists to restrict melanoma tumor growth." (PMID 41597427, 2026). "We also found that the therapeutic success was not limited to the TLR7 agonist IMQ, as a different TLR7/8 agonist (Resiquimod, R848) was also effective in melanoma." (PMID 39849091, 2025). "Their group also explored the impact of adipokines and gut microbiome on melanoma outcomes and the anti-tumor effects of TLR7/8 agonists on NK cells in melanoma models." (PMID 41141601, 2025). "Analysis of cohorts of patients with melanoma demonstrates DC-specific TLR7/8 upregulation by IFN-I, supporting the translational potential of combining systemic IFN-I and topical IMQ to improve immunotherapy of topically accessible tumors." (PMID 39849091, 2025). "Here, the 4T1 breast cancer model and the B16 melanoma model were applied because the antitumor effects of TLR7 agonists or BRD4 inhibitors were decided previously in these two types of cancers." (PMID 38203835, 2024). "HLJD enhanced the therapeutic benefits of ICIs in melanoma, through increasing reactive oxygen species (ROS), promoting the TLR7/8 pathway, and activating IFN-Is signaling, which in turn activated DCs and T cells." (PMID 38605368, 2024). "In our previous publication, we showed that the unadjuvanted flu vaccine modulates TLR7 expression leading to anti-tumor response in a murine model of melanoma." (PMID 38476365, 2024). "Imiquimod, a Toll-like receptor 7 (TLR7) agonist is routinely used for topical administration in basal cell carcinoma and stage zero melanoma." (PMID 36913398, 2023). "TLR7/8 agonist NKTR-262 increased CD11c dendritic cell recruitment to tumors in melanoma, but a trial of NKTR-262 in combination with bempegaldesleukin with or without nivolumab was terminated." (PMID 37686661, 2023). "Recently, it was reported that the TLR9 agonist PRINT-CpG was effective in promoting tumor regression in mouse models of non-small cell lung cancer, and the TLR7/8 agonist also has an antitumor effect in melanoma, which was consistent with this study." (PMID 37296415, 2023). "BDB001 and CV8102 are other TLR7/8 agonists being investigated in solid tumors and melanoma, respectively." (PMID 37686661, 2023). "For example, the injection of TLR7/TLR8 agonists in a subcutaneous model of melanoma rewired macrophages into proinflammatory cells increased T-cell infiltration." (PMID 35158779, 2022). "In this study, we found that B16 melanoma responds better to monotherapy with anti-PD-L1 antibody and to combination therapy with anti-PD-L1 antibody plus TLR-7/8 agonist in the presence of B cells." (PMID 35720386, 2022). "Previously, we reported that PD-1 pathway blockade enhanced the therapeutic efficacy of injectable TLR-7/8 agonist against melanoma." (PMID 35720386, 2022).
melanoma (continued). "In this experiment, a novel whole-tumor-cell vaccine was prepared by coupling SZU-106, a small-molecule TLR7 agonist, with Aza-stimulated B16-F10 melanoma cells." (PMID 35805071, 2022). "For instance, in skin malignancies such as melanoma and basal cell carcinoma, the TLR7 agonist imiquimod can enhance the cytotoxic function of pDCs, which mainly depended on TRAIL and GZMB secretion." (PMID 34964283, 2022). "For these reasons, active pDCs in vitro and TLR7/9 agonists are applied in the immunotherapy of various cancers, such as breast cancer and melanoma, and have achieved encouraging outcomes." (PMID 34964283, 2022). "TLR3 agonist poly-ICIC and TLR7/8 agonist Resiquimod have been combined with tumor vaccines in the treatment of melanoma (NCT02126579) and advanced tumors refractory to conventional treatment (NCT00948961)." (PMID 36479129, 2022). "Meanwhile, in a preclinical melanoma mouse model, the TLR7 agonist IMQ improves T and NK cell function during BRAF-targeted therapy." (PMID 36476317, 2022). "852A is another TLR7 agonist which has been tested for the treatment of melanoma and gynecological cancers." (PMID 35158779, 2022). "TLR7 agonist was used as a vaccine adjuvant in nine malignant melanoma patients, resulting well-tolerated and inducing tumor pDC infiltration." (PMID 32054102, 2020). "The role of TLR7 or IFNAR signaling in pDC-mediated cytotoxicity was confirmed by using mouse models of melanoma." (PMID 32054102, 2020). "The TLR7 agonist imiquimod, approved for the topical treatment of squamous and basal cell carcinoma, was reported to be safe also in the treatment of melanoma and skin lesions of metastatic breast cancer, enhancing accumulation of immune cells in the lesions." (PMID 32708142, 2020). "Overall, TLR7 induction suppresses the metastatic potential of melanoma through inducing a Th1-like response." (PMID 32455916, 2020). "Our previous study demonstrated that stimulation with a TLR7 agonist enhances anticancer effects via autophagic cell death during radiotherapy for melanoma, suggesting that TLR7 agonists can induce autophagic cell death." (PMID 32765474, 2020). "For instance, NKTR-262, another TLR7/8 agonist, is currently under evaluation for the treatment of melanoma and other advanced cancers in combination with the checkpoint inhibitor nivolumab (NCT03435640)." (PMID 31805946, 2019). "As a proof of concept, we probed the therapeutic potentials of the combination of MEK1/2 inhibitor and TLR7 agonist in a murine model of subcutaneous melanoma." (PMID 31507609, 2019). "The four highest binding hexavalent mannoside structures were conjugated to a model melanoma gp100-peptide antigen and further equipped with a Toll-like receptor 7 (TLR7)-agonist as adjuvant for DC maturation, creating a trifunctional vaccine conjugate." (PMID 31637232, 2019). "Activation by toll-like receptor 7 (TLR7) ligand reverses pDC immunosuppressive function to such an extent that their administration to melanoma patients induces tumor-specific CD4+ and CD8+ T-cell responses." (PMID 29619026, 2018). "Plasmacytoid dendritic cells are also thought to be involved in the pathogenesis of tumor and autoimmunity characterized by IFN-I via TLR-7/9 ligands in breast cancer and melanoma." (PMID 29085361, 2017). "This study was performed to evaluate the synergistic anti-cancer and anti-metastatic effects of the TLR7 agonist imiquimod (IMQ) during radiotherapy for melanoma." (PMID 28212561, 2017). "The current data provide the first evidence that IMQ has the potential to suppress metastasis in a murine melanoma model via a TLR7-induced pathway." (PMID 28212561, 2017). "The present study shows that the TLR7 agonist IMQ promotes autophagic cell death in melanoma cell lines and enhances radiosensitivity in an in vivo mouse melanoma model, and these effects are correlated with the anti-cancer immune response in tumor lesions." (PMID 28212561, 2017).
melanoma (continued). "The results showed that both melanoma cell lines expressed the TLR7 transcript and that the level of TLR7 expression in the cells was not changed by treatment with IMQ alone or IMQ and 3-MA, an autophagy inhibitor." (PMID 28212561, 2017). "In melanoma treatment using the TLR-7 agonist imiquimod, infiltrating pDCs are capable of producing IFN-α and inducing complete regression or significant reduction of melanomas." (PMID 29085361, 2017). "In contrast, TLR agonists, specifically targeting TLR7, 8, and 9, have been successfully used as therapeutics for melanoma and BCC, functioning by recruiting dendritic cells and inducing T-cell responses." (PMID 24744758, 2014). "In contrast, TLR agonists, specifically targeting TLR7, 8, and 9, have been successfully used as therapeutics for melanoma and basal cell carcinoma (BCC), functioning by recruiting dendritic cells and inducing T-cell responses." (PMID 24744758, 2014). "Another example could be The Aza-BFcell-106 vaccine, which couples Aza-stimulated melanoma cells with a TLR7 agonist and showed enhanced immunogenicity and therapeutic potential in melanoma." (PMID 41601679, 2026). "TLR7-deficient (TLR7-/-) mice bearing B16 melanoma tumors treated with FluVx did not experience reduction in tumor progression which was found in TLR7-competent, C57BL/6J (WT) mice." (PMID 38476365, 2024). "Interestingly, TLR7 signaling activated plasmacytoid dendritic cells (pDCs) leading to killing of murine melanoma cells through stimulation of NK cells and activating CD8+ cytotoxic T-cells." (PMID 37936697, 2023). "Hence, in this study, we first used Aza to stimulate B16-F10 melanoma cells to express TLR3 on the cell surface and further linked it with SZU-106, a TLR7 agonist, to the cell surface with a pegylated linker." (PMID 35805071, 2022). "TLR7 agonists show strong immunostimulatory activity, inducing tumor-specific immune responses and reducing the growth of colon, renal, and breast carcinomas and melanoma 14-16." (PMID 34975325, 2022). "Analysis results of normalized gene expression and corresponding clinical data of patients with skin cutaneous melanoma demonstrated that TLR7 and 8 expressions correlated with the expression of immune biomarkers and positively predicted the clinical outcome of patients with melanoma." (PMID 36476317, 2022). "We sought to determine whether B cells play an essential role in the anti-melanoma immune response mediated by combination therapy with anti-PD-L1 antibody and TLR-7/8 agonist." (PMID 35720386, 2022). "We also confirmed the dose-dependency of p(Man-TLR7-PDS)in B16F10 melanoma." (PMID 36313164, 2022). "Indeed, we found B cell chemokine CXCL13 was required to generate optimal anti-melanoma effect and prolonged mouse survival in response to combination therapy with anti-PD-L1 plus TLR-7/8." (PMID 35720386, 2022). "Interestingly, Aspord and co-workers additionally demonstrated that the development of melanoma was strongly inhibited by imiquimod treatment (a TLR7 agonist) using an innovative melanoma-bearing humanized mouse model." (PMID 34737750, 2021). "Moreover, activation of plasmacytoid dendritic cells via TLR7 signaling interestingly resulted in murine melanoma cell killing." (PMID 34124272, 2021). "Based on our in vitro studies, we postulated that MEK1/2 inhibitor may boost TLR7-mediated anti-melanoma interferon responses in vivo." (PMID 31507609, 2019). "For example, local delivery of a TLR7/8 agonist 3 M-052 boosted systemic antitumor immunity by repolarizing TAMs to M1-like phenotypes and resulted in tumor regression in a mouse model of subcutaneous melanoma." (PMID 31805946, 2019). "However, the combination treatment significantly improved the animal survival and retarded melanoma progression when compared to TLR7 agonist single treatment." (PMID 31507609, 2019). "In contrast, TLR7 agonist alone delayed mortality and slowed melanoma growth." (PMID 31507609, 2019).
melanoma (continued). "Similar to lung and breast cancer, TLR7 agonists (eg., imiquimod) activate the immune response in skin cancers (melanoma, squamous cell carcinoma, and basal cell carcinoma) and several agonists are currently in clinical trials for melanoma (imiquimod (NCT01678352) and resiquimod (NCT01748747))." (PMID 29190881, 2017). "Also, pDCs stimulated with agonists for TLR7 and 9 upregulated the surface expression of TRAIL in a type I IFN-dependent manner, causing the lysis of Jurkat cells and melanoma cell lines SKMel2 and WM793." (PMID 29050360, 2017). "Based on the fact that TLR7 and 9, the target receptors of imiquimod, reside within the ER, we next asked, whether the exposure of melanoma cells to imiquimod triggers ER stress, and if so, what is the result of ER stress on calcium homoeostasis?" (PMID 26578344, 2016). "This study provides new perspectives on NK cell phenotype in solid tumors after TLR7/8 agonist administration, and our findings on NK cell dynamics during treatment with Toll-like receptor 7/8 agonists in melanoma could be used to establish new approaches in cancer immunotherapy." (PMID 41597427, 2026). "In addition to TLR9 stimulated cytotoxicity of NK cells on B16 melanoma cells, the secretion of inflammatory cytokines as IFNγ and IL-12 was promoted via TLR7/8 activation, which in order aided the NK cells to eliminate the HNSCC cells and B16-F10 melanoma cancer cells." (PMID 37936697, 2023). "On the other hand, immunologically “hot” tumors such as melanoma, head and neck, and lung, that are generally more sensitive to immune checkpoint blockade may also benefit from TransCon TLR7/8 Agonist through further potentiation of antigen presentation and of induction of local inflammation." (PMID 36123697, 2022). "However, our concept is unique, because of the specific combination of TLR ligands (particularly TLR2, TLR3, and TLR7/8), which seems to have an extraordinary effect on innate immunity activation and tumor elimination, as previously presented in melanoma and pancreatic adenocarcinoma mouse models." (PMID 31083581, 2019). "In this study, we found that HLJD significantly upregulated the expression of TLR7 and TLR8 and activated IFN-Is signaling in melanoma tissues, acting in part as a safe and cost-effective TLR agonist." (PMID 38605368, 2024). "Imiquimod (IMQ) is a Toll-like receptor 7 (TLR7) agonist used for the in situ treatment of cutaneous squamous cell carcinoma, superficial basal cell carcinoma (BCC), cutaneous malignant melanoma metastases, and precursor lesions of actinic keratosis." (PMID 39272918, 2024). "Based on a set of microscopic, functional and in silico analyses, we demonstrated that the melanoma milieu directly impairs IFN-α and CXCL10 production by pDCs via TLR-7/9 and cGAS-STING signaling pathways." (PMID 38239354, 2023). "The topical application of TLR7 agonist IMQ in combination with other drugs, such as ipilimumab, for patients with malignant melanoma has been reported with successful results." (PMID 36476317, 2022). "Secretion of IFNγ and IL-12 and other inflammatory cytokines via TLR7/8 stimulation enabled NK cells to kill HNSCC and melanoma B16 tumor cells while TLR9 triggered cytotoxic activity of these cells on melanoma cells." (PMID 34124272, 2021). "Here we treat B16F10 melanoma with agonists of the endosomal TLRs TLR3, TLR7 and TLR9 to understand the influence of these agents on immune polarization in a ‘cold’ tumor model." (PMID 34381732, 2021). "Using single-cell RNA-sequencing, we address this by comparing the tumor immune composition of B16F10 melanoma following treatment with agonists of TLR3, TLR7, and TLR9." (PMID 34381732, 2021). "Encouraging results were obtained in mice tumor models of melanoma, breast cancer and others, with TLR3, TLR7, TLR8 and TLR9 ligands." (PMID 32708142, 2020).